EDEM1 (ER degradation enhancing alpha-mannosidase like protein 1)
Diseases named in the same sentence as EDEM1 in open-access papers (continued):
Sharing a sentence is not in itself a finding about the gene and the disease.
tumor (11 papers, 2012 to 2025). "Given the association between EDEM1 and ER stress, we wonder whether EDEM1 could modulate cellular ROS production in tumor cells." (PMID 40735463, 2025). "In this study, ER-associated degradation (ERAD)-related protein EDEM1 (ER degradation enhancing α-mannosidase-like 1) plays a vital role in DOX-induced ER stress, which is up-regulated in tumor cells and tissues." (PMID 40735463, 2025). "The terminal deoxynucleotidyl transferase-mediated dUTP nick end labeling (TUNEL) assay validated that EDEM1 overexpression inhibited tumor apoptosis both in normal conditions and in DOX-induced conditions." (PMID 40735463, 2025). "Our study proved that EDEM1 can alleviate the autophagy of tumor cells and weaken the apoptosis process." (PMID 40735463, 2025). "The IHC analyses of Ki67 and CD31 demonstrated that EDEM1 overexpression promoted tumor proliferation and angiogenesis." (PMID 40735463, 2025). "In our study, levels of EDEM1 were markedly decreased in CRC tissues compared with normal tissues, an association that correlated with tumor stage." (PMID 33461166, 2021). "EDEM1 expression also showed significant differences in correlation with the patient's sex, tumor type, and stage." (PMID 33461166, 2021). "Also, IHC staining of GRP78 confirmed that DOX enhanced ER stress in tumor tissue, while the overexpression of EDEM1 attenuated the ER stress level induced by DOX." (PMID 40735463, 2025). "Given that microRNAs (miRNAs) are well-documented for their ability to inhibit gene expression through posttranscriptional regulation of protein accumulation and their established role in tumor development and progression, we focused on investigating whether EDEM1 is regulated by miRNAs." (PMID 40735463, 2025). "Inspired by these findings, we speculate that modulating ER stress signaling and disrupting tumor cell adaptive responses through the use of plant-derived compounds, EDEM1 inhibitors, or ER stress inducers may represent a novel strategy to overcome chemoresistance in TNBC." (PMID 40735463, 2025). "The up-regulation of EDEM1 enhanced tumor resistance to ER stress and DOX in TNBC cells, while the knockdown of EDEM1 exerted converse effects in DOX-resistant 231/DOX cells." (PMID 40735463, 2025). "We utilized qRT-PCR to validate increased expression of various transcripts related to the IRE1α/XBP1 arm of the UPR, such as IRE1 (gene name: Ern1), Xbp1, Dnajb9, Edem1, and CHOP (gene name: Ddit3) in GA muscle of KPC tumor-bearing mice compared to control mice." (PMID 40655023, 2025). "(A) mRNA expression of ER-stress markers Edem1, Ero1b, Grp94, Herp, Atf4, Eif2ak3, Ddit3, and Hspa5 in liver tissue from healthy mice; and tumor tissue and surrounding non-tumoral tissue from mice with DEN-induced HCC." (PMID 33103995, 2020). "Furthermore, EDEM1 promotes ERAD and enhances the antioxidant capacity of tumor cells." (PMID 40735463, 2025).
infection (7 papers, 2013 to 2025). The state of being infected such as from the introduction of a foreign agent such as serum, vaccine, antigenic substance or organism. "Quantitative real time PCR analysis showed that the transcription levels of both XBP-1 gene (~9 fold) and EDEM-1 (~16 fold) increased at 48 h post infection." (PMID 23356742, 2013). "Interestingly, only EDEM1, which is involved in the clearance of misfolded proteins, was transiently up-regulated at day 1 and day 2 post-infection, whereas BiP, DDIT3 and ATF4 mRNA expression were not affected." (PMID 34224022, 2021). "In cells expressing UL148 (i148HA), we observed that calnexin, HRD1, EDEM1, and VCP colocalized with UL148 at prominent globular structures reminiscent of those observed during infection." (PMID 31822584, 2019). "Our data suggest that the IRE1α pathway could be activated at the late stage of infection when high levels of the total XBP1 gene and the downstream EDEM1 gene were detected." (PMID 40248709, 2025).
cancer (5 papers, 2020 to 2025). A tumor composed of atypical neoplastic, often pleomorphic cells that invade other tissues. "Given these multifaceted roles of miRNAs in cancer biology and therapy, we specifically focused on miRNAs as potential upstream regulators of EDEM1 expression and function." (PMID 40735463, 2025). "Moreover, the expression of miR-32-5p was negatively correlated with EDEM1 expression in cancer cells, consistent with the predicted results by the StarBase database." (PMID 40735463, 2025). "Based on the well-established role of Nrf2 activation in suppressing ferroptosis primarily achieved through the up-regulation of antioxidant genes and our findings, we proposed that EDEM1 could alleviate oxidative stress and promote cancer cell survival at both the ER stress and ferroptosis levels." (PMID 40735463, 2025). "In the Cancer Cell Line Encyclopedia (CCLE) database, ATIC was found to be overexpressed, while CDKN1A, DNAJB9, EDEM1, and GABARAPL1 exhibited lower expression levels, aligning with the gene expression patterns observed in our model equations." (PMID 41040512, 2025). "(A) mRNA-expression of ER-stress markers ATF6, ATF4, EIF2AK3, GADD34, EDEM1, DDIT3 and HSPA5, in stellate cells (LX2) co-cultured with cancer cells (HepG2 or Huh7) and treated with 4μ8C or control." (PMID 33103995, 2020).
EDEM1 also shares sentences with these, for which no sentence is quoted: lung adenocarcinoma (2 papers); bladder cancer (1); co-infection (1); endothelial dysfunction (1); Hepatic fibrosis (1); Impaired glucose tolerance (1); metastatic melanoma (1); nasopharyngeal carcinoma (1); periodontitis (1); prostate tumour (1); retinal degeneration (1); T-cell lymphoma (1); triple-negative breast carcinoma (1).